IL6 (interleukin 6)
Diseases named in the same sentence as IL6 in open-access papers (continued):
Sharing a sentence is not in itself a finding about the gene and the disease.
psoriasis (continued). "The heatmaps revealed an increase in several classic proinflammatory cytokines such as Tnf, Il6, Il1a, Il23α and a small number of chemokines, including Ccl19, Ccl20, Cxcl13, and Cxcl5, which are typically elevated in psoriasis patients, in CD169+ macrophages." (PMID 38891893, 2024). "Proinflammatory adipokines (TNF-α, IL-1, IL-6, and leptin) play a role in keratinocyte proliferation, and IL-1 is involved in molecular adhesion in the pathophysiology of psoriasis." (PMID 38473907, 2024). "For instance, AZ17 is a BsAb in preclinical stages that combines binders specific for IL‐23 and IL‐6, and it has demonstrated high efficacy in a human xenograft transplantation model of psoriasis." (PMID 38533646, 2024). "Key active compounds, such as piperine, piperlongumine, α-humulene, schizandrin A, schizandrin II, and torilin, were prioritized for their ability to target psoriasis-associated proteins, including STAT3, TNF, IL-6, and NF-κB." (PMID 39590306, 2024). "In a mouse model of skin inflammation induced by imiquimod, the anti-psoriasis effect of tea extract was evaluated by measuring its inhibition of several pro-inflammatory cytokines such as IL-1, IL-6, IL-22, FN, IFN-γ, and TNF-α." (PMID 38542915, 2024). "The present study showed that reduced quality of life and elevated serum IL-6 levels were predictors of poor drug survival in patients with moderate to severe psoriasis." (PMID 37634972, 2024). "IL-6 is upregulated in psoriasis and is crucial to inflammatory crosstalk and pathways, acting synergistically with IL-1 and TNF-α." (PMID 38666958, 2024). "Remarkably, treatment of 17A-Lytaca markedly decreased the mRNA expression of IL-17A and its downstream psoriasis-related inflammatory cytokines in the skin lesion, including IL-6, CCL-20, and IL-22, compared with the positive group." (PMID 38396109, 2024). "The etiology of psoriasis involves up-regulation of several pro-inflammatory cytokines, including IL-6, IL-8, IFN-γ, and TNF-α." (PMID 39777115, 2024). "Researchers revealed that pro-inflammatory cytokines (IL-1β, IL-6, and IL-12) were significantly increased and anti-inflammatory cytokines (e.g., IL-10) were decreased in mice with psoriasis after sleep deprivation." (PMID 38347543, 2024). "Several studies concluded that the secretion of IL-1, IL-6, and IL-13 by mast cells is activated by IL-33, highlighting its role in psoriasis." (PMID 38666958, 2024). "Higher mean serum concentrations of IL-6, total cholesterol (TC), low-density lipoprotein, and triglycerides were found in patients with PsA compared to those with psoriasis alone." (PMID 39429270, 2024). "A notable feature of these changes is the new onset or exacerbation of psoriasis during anti-TNFα or anti-IL-6 therapy, with such reactions being more prevalent in women and typically presenting as palmoplantar impetigo." (PMID 39684717, 2024). "Based on the pathophysiology of the disease, we expected to find lower IL-6 and IL-12 levels in treated patients with psoriasis." (PMID 39044928, 2024). "Of note, just recently, NLRs (and the cytokine IL-6) were found to be predictive biomarkers in psoriasis patients for treatment response under TNFalpha inhibitors." (PMID 38127137, 2024). "It was reported that pro-inflammatory cytokines and mediators such as IL-17A, IL-22, IL-23, IL-6, IL-1β, and p65 play an important role in the development and maintenance of psoriasis." (PMID 39296901, 2024). "They exhibit anti-inflammatory properties by inhibiting key cytokines such as TNF-α, IL-6, IL-8, and IL-24, which play pivotal roles in the pathogenesis of psoriasis." (PMID 39199158, 2024). "IL-6 gene expression was higher in patients with PsA than in patients who only had psoriasis skin lesions, and it was closely related to joint disorders." (PMID 39335643, 2024). "The reduction in IL-6 abundance was much more pronounced than in the first experimental approach, where C3bot was applied after manifestation of psoriasis phenotype." (PMID 37707681, 2024).
psoriasis (continued). "Short sleep and psoriasis can also be linked through inflammatory networks, particularly tumor necrosis factor-α and IL-6, related to psoriasis pathogenesis and sleep regulation." (PMID 38988999, 2024). "Effectively, Sialostatin L didn’t show any significant inhibition of IL-6, although psoriasis-related pro-inflammatory cytokines (TNF-α, IL-22, IL-23/IL-17) expression was reduced." (PMID 38444844, 2024). "Activated macrophages can produce cytokines such as TNF-α, IL-6, and IL-23, which are critical for the differentiation of Th17 cells, in psoriasis lesions." (PMID 38891893, 2024). "Serum levels of several proinflammatory cytokines, including TNF-α,IFN-γ,IL-6,IL-8,IL-12,IL-17A and IL-18 were elevated in individuals diagnosed with psoriasis compared to healthy controls, suggesting that psoriasis develops systemically." (PMID 38504983, 2024). "Genetic polymorphisms in cytokines such as interleukin-1 (IL-1), interleukin-6 (IL-6), and TNF-α have been associated with an increased risk of developing both psoriasis and related systemic diseases, indicating a shared genetic basis for these conditions." (PMID 39189252, 2024). "Here, the biological effectiveness of ursolic acid formulations in psoriasis treatment was demonstrated, observed by the diminished IL-6 and IL-8 production and limiting effect on the M5-induced proliferation." (PMID 38672088, 2024). "TNF-α and IL-6 are related to the pathophysiology of psoriasis and serve as powerful therapeutic target." (PMID 38550599, 2024). "In atherosclerotic conditions, platelet-derived EVs stimulate the activity of IL-1, IL-6, and IL-8, all of which are important mediators in psoriasis." (PMID 38927529, 2024). "The target proteins of these active compounds, including IL1B, TNF, STAT3, IL6, NOS2, and NFKBIA, were found to be directly associated with psoriasis-related disease proteins." (PMID 39590306, 2024). "Specifically, Ligilactobacillus and Anaeroplasma are positively correlated with various psoriasis-related factors such as IL-6, IL-17A, IL-22, and IL-23, while Rikenella, Alistipes, and Mucispirillum are negatively correlated with them." (PMID 39170985, 2024). "IL-6 is a pleiotropic proinflammatory cytokine that is elevated in serum and skin lesions in patients with psoriasis." (PMID 39328313, 2024). "For the other two inflammatory cytokines, IL-6 and IL-12, we were unable to obtain statistically significant data, most likely owing to the small group of patients, although the data suggested lower levels of both IL-6 and IL-12 in the psoriasis group." (PMID 39044928, 2024). "IL-1β and IL-6 are commonly upregulated inflammatory cytokines during psoriasis and stimulation of keratinocytes with TLR agonists have been shown to induce their expression." (PMID 39586195, 2024). "Given the pivotal roles of pro-inflammatory cytokines such as IL-6, TNF-α, IL-1β, and Th17-associated cytokines, in psoriasis development, we compared their expression levels in IMQ-treated WT and CD169-DTR mice." (PMID 38891893, 2024). "Poor quality of life and elevated baseline serum IL-6 level predicted treatment interruption in patients with moderate to severe psoriasis." (PMID 37634972, 2024). "Further Western blots showed that the abundance of IL-6 was upregulated by cytokine mixture, as expected for a psoriasis phenotype." (PMID 37707681, 2024). "Patients with psoriasis have elevated levels of proinflammatory cytokines, such as IL-6 and tumor necrosis factor-alpha, contributing to systemic diseases." (PMID 39429270, 2024). "Even closer to the findings of our study in PSC, high exposure to IL‐6 in lesional tissue led to a dampened function of Tregs in patients with psoriasis." (PMID 38607233, 2024). "Other than having a role in MHC class I antigen presentation, ERAP1 is involved in the activation of inflammasome pathways and production of cytokines and chemokines involved in psoriasis development (i.e., IL-6, TNF-α, and CCL2)." (PMID 38495872, 2024).
psoriasis (continued). "Overexpression of TNF-α results in excessive production of proinflammatory cytokines like IL-6, IL-8, IL-12, and IL-18, driving a transformation of the psoriasis phenotype to pustular psoriasis." (PMID 38695018, 2024). "Then, to investigate the mechanism of TGF-β induction, we stimulated healthy keratinocytes (NHEK) in vitro with a number of cytokines characterizing the psoriasis microenvironment including IL-1β, IL-6, IL-17A, IL-19, IL-22, IL-23, IL-26, and IFN-γ." (PMID 37391412, 2023). "The JAK/STAT3 and JAK/STAT1 signaling pathways play an important role in the development of psoriasis when triggered by IL-6 and IFN-γ, which are produced by dendritic cells and T-lymphocytes." (PMID 36838711, 2023). "Following this, knowing that IL-6 is an NFκB-dependent cytokine associated with ADAMTS7 production, we assessed this association and found a positive correlation in psoriasis." (PMID 36677041, 2023). "The chronic inflammation and increased production of IL-6 and IL-17A in psoriasis influence adipocytes differentiation and their capability of adipokine and chemokine synthesis and increase in visceral and subcutaneous white adipose tissue (WAT)." (PMID 37762217, 2023). "An amalgamation of metabolic and immune findings revealed that certain molecular features, including IL-6, IL1-ra, DMG, CCL4, IIe, Gly, and IL-8, offer diagnostic precision in differentiating newly diagnosed psoriasis patients from healthy individuals." (PMID 38035065, 2023). "Imiquimod was observed to induce more severe psoriasis in obese mice, and the levels of IL-6, TNF- α, and Th17 cells, were simultaneously elevated." (PMID 36982669, 2023). "Serum cytokines, including TNF-α, IFN-γ, IL-2, IL-6, IL-22, and IL-23, are primarily produced by Th1 and Th17 cells and have emerged as potential biomarkers for psoriasis." (PMID 38239345, 2023). "Remarkably, IL-4 is a negative regulator of Th1 and Th17 cells, which can inhibit the secretion of IL-1b and IL-6 by psoriasis epidermal cells." (PMID 37408052, 2023). "After 6–8 weeks of administration, this probiotic strain reduces plasma CRP levels in all three conditions, reduces TNFα in chronic fatigue syndrome and psoriasis, and reduces IL-6 in UC and chronic fatigue syndrome." (PMID 38055306, 2023). "IL‐6 is essential for differentiation of T‐helper cells (Th‐17) cells and pathogenesis of psoriasis, through facilitation of keratinocyte growth, activation and neutrophil differentiation." (PMID 37275420, 2023). "IL‐6 is another important member of the cytokine network that regulates keratinocyte proliferation and differentiation in psoriasis." (PMID 38156380, 2023). "In turn, pro-inflammatory cytokines such as TNF-α, IL-1β, and IL-6, which are increased in psoriasis, can activate LOX-1, promoting the uptake of ox-LDL by macrophages." (PMID 37234169, 2023). "The aggravation of symptoms was related to increased production of the psoriasis-related proinflammatory cytokines IL-6 and TNF-α." (PMID 36982669, 2023). "Similar to psoriasis, studies have shown that IL-6 is involved in regulating inflammation-related thrombosis." (PMID 37391801, 2023). "IL‐6 levels were significantly increased in the plasma of patients with psoriasis versus healthy controls (***p < .001)." (PMID 38156380, 2023). "The upregulation of other cytokines, such as IL‐6, IL‐12, IL‐22, IL‐29, IL‐36, IL‐1 β, and tumor necrosis factor‐α, is also involved in the pathogenesis of psoriasis." (PMID 38156380, 2023). "Its expression correlates with the severity of psoriasis, as well as with serum levels of IL-6, fetuin-A, and PTX3." (PMID 38052851, 2023). "We have previously found an association between low levels of IL-6 and TNF-α at baseline and a response to brodalumab in patients with psoriasis." (PMID 37047086, 2023). "Owing to its excessive activation and dysregulation of receptor signaling in T cells, IL‐6 is involved in the pathogenesis of psoriasis." (PMID 38156380, 2023).
psoriasis (continued). "Patients with SMO deficiency had a higher number of TLR-2 + TLR-4 -granulocytes and increased levels of serum IL-6 and IL-8 expression, which is consistent with psoriasis patients." (PMID 37234169, 2023). "Conversely, the overexpressed IL-17 cytokine in psoriasis leads to the activation of the NF-ᴋB pathway and the production of other proinflammatory cytokines-IL-1β, IL-6, and TNF-α." (PMID 38003284, 2023). "The activated JNK pathway in keratinocytes can mediate the recruitment of immune cells in psoriasis by regulating the production of inflammatory cytokines/chemokines, such as IL-6, IL-8, IL-23, IFNγ and TNFα, and CCL20 and hβD-2." (PMID 38008779, 2023). "Paraffin‐embedded skin specimens from patients with psoriasis and imiquimod‐induced psoriasis‐like mice were collected to determine the expression profiles of IL‐6 in the epidermal tissues." (PMID 38156380, 2023). "It has been reported that various cytokine levels such as IL-12, IL-6, IL-17, and TNF-α, which are known to increase in psoriasis, cause an increase in NLR levels." (PMID 37731441, 2023). "The results revealed that IL‐6 levels were markedly increased in the plasma of patients with psoriasis, compared to healthy control." (PMID 38156380, 2023). "Monocytes showed a significant increase in chemotactic response in psoriasis, and also produce some cytokines of major importance in psoriasis, such as IL-1, IL-6, and tumor necrosis factors, among others." (PMID 36865550, 2023). "Elevation of TRIM27 level and activation of IL-6/STAT3 signalling pathway were found in an in vivo psoriasis-like inflammation model, whereas inhibition m6A methylation strongly alleviated the inflammation." (PMID 38146129, 2023). "To further explore the effect of CMX on the pathogenesis of psoriasis, we cultured HaCaT cells and incubated them with IL-6 to mimic the abnormal proliferation of keratinocytes in vitro." (PMID 36838711, 2023). "The pro-inflammatory mediators associated with psoriasis are IL1B, IL2, IL6, IL12, IL15, IL17, IL18, and IL20." (PMID 37569685, 2023). "Keratinocytes in psoriatic lesions are potentially rich in LL-37 and can induce the production of TNF-α and IL-6 in dendritic cells, further indicating that neutrophils are involved in worsening psoriasis." (PMID 37964882, 2023). "The recruitment of circulating leukocytes to the epidermis and the production of pro-inflammatory factors, such as TNF-α, IFN-γ, IL-6, IL-8, IL-23, IL-1β, and IL-17A play a crucial role in the development of psoriasis." (PMID 37346040, 2023). "This study aims to develop a low-cost, simple-to-manufacture, and user-friendly label-free electrochemical point-of-care device for the rapid detection of IL-6 in patients with psoriasis." (PMID 38025060, 2023). "The results indicate that adiponectin exerts anti-inflammatory effects in psoriasis by reducing the production of IL-6 and TNF-α." (PMID 36675592, 2023). "IL-6 effectively triggers keratinocyte proliferation, and its role has been studied in the wound healing process and in skin diseases, including psoriasis, correlated with epidermal hyperplasia." (PMID 38102220, 2023). "Interleukin‐6 (IL‐6) is mainly involved in regulating T cell functions and development in patients with psoriasis." (PMID 38156380, 2023). "The JAK/STAT3 and JAK/STAT1 signaling pathways are crucial in psoriasis development via the stimulation of IL-6 and IFN-y, which are produced by dendritic cells and T lymphocytes." (PMID 38202691, 2023). "A chemiluminescence immunoassay was used to detect plasma levels of IL‐6 in healthy donors and patients with psoriasis." (PMID 38156380, 2023). "In this study, we found that plasma IL‐6 levels were higher in patients with psoriasis than in healthy populations and were abnormally expressed in psoriatic lesions and imiquimod‐induced psoriasis‐like lesions." (PMID 38156380, 2023). "We showed that IL‐6 levels are significantly increased in the plasma of psoriasis patients versus healthy donors." (PMID 38156380, 2023).
psoriasis (continued). "Leptin has been shown to increase the synthesis of pro-inflammatory mediators involved in the pathogenesis of psoriasis, such as IL-1, IL-6, TNF-α, and CXCL8." (PMID 36675592, 2023). "For instance, Tregs can convert to IL-17-like cells under inflammatory conditions, especially in the presence of IL-6, which is a cytokine highly up-regulated in psoriasis." (PMID 36901778, 2023). "Low adiponectin levels in patients with psoriasis are associated with increased TNF-α and IL-6 levels and are inversely correlated with PASI scores." (PMID 38003284, 2023). "The expression of TNF-α and IL-6 as well as IL-22, IL-23, and IL-17 family of cytokines (IL-17A, IL-17E, and IL-17F) was significantly increased in psoriasis skin lesions." (PMID 35663991, 2022). "These cells are a significant source of proinflammatory cytokines, especially tumor necrosis factor α (TNF-α), and interleukin-6, which lead to the progression of psoriasis." (PMID 35335900, 2022). "Mechanically, miR-let-7b inhibited ERK signaling pathway through targeting IL-6, resulting in the acceleration of keratinocyte differentiation in psoriasis." (PMID 35075118, 2022). "The activation of NF-κB pathways is the hallmark of psoriasis, and results in the production of excessive inflammatory cytokines (e.g., TNF-α, IL-6, IL-17), which leads to the progression of psoriasis." (PMID 35335900, 2022). "For instance, in the presence of TGF-ß and IL-6, naive T cells differentiate into Th17 cells, producing effectors that drive psoriasis immunopathogenesis." (PMID 36741386, 2022). "Consistent with the ameliorated psoriasis‐like phenotype, the mRNA levels of genes related to the IL‐23/IL‐17 axis, such as Il23a, Il17a, and Il22, and the expression of Tnfa, Il6, and Il1b was decreased in the skin." (PMID 34936223, 2022). "TNF-α and IL-6 mRNA expressions were reduced in the skin lesions of mice with C23-treated IMQ-induced psoriasis, and this effect was accompanied by inhibition of the NF-κB and ERK1/2 signaling pathways." (PMID 36110097, 2022). "Analysis of the inflammatory factors in the serum showed that the levels of TNF-α, IL-6, IL-1β, and IL-17 were significantly higher in psoriasis patients than in HCs." (PMID 35927231, 2022). "IL-6 plays a central role by cross-talk with cytokines of the IL-23/Th17 axis in the development of psoriasis." (PMID 35216231, 2022). "Activation of PI3K and STAT3 promotes the excessive proliferation and abnormal differentiation of KC, infiltration of inflammatory cells, and secretion of cytokines (IL-6, IL-17, IL-22, and IL-23) in psoriasis." (PMID 35720176, 2022). "The increased levels of inflammatory markers, such as tumor necrosis factor-α (TNF-α), interleukin-6, and C-reactive protein, have indeed been found in the lung tissue of patients with psoriasis." (PMID 35163689, 2022). "It has been reported that keratinocytes in psoriasis patients are under stress and can secrete TNF-α and IL-6 to activate dendritic cells (DCs) to promote the progression of psoriasis." (PMID 36618400, 2022). "Proinflammatory cytokines, whose production is markedly increased in psoriasis (TNF-α, IL-17, IL-23, and IL-6) all contribute significantly to insulin resistance in patients with psoriasis." (PMID 35743091, 2022). "In psoriasis, with the presence of IL-6 and transforming growth factor-β, CD4+ T cells will undergo differentiation into Th17." (PMID 35203707, 2022). "The fact that both serum malondialdehyde and IL-6 levels are elevated in individuals with psoriasis and coronary heart disease emphasizes the involvement of oxidative stress in the pathogenesis of these afflictions." (PMID 35204165, 2022). "The present study demonstrates the downregulating effects of forsythoside A on IL-6 and IL-17 expression, indicating that forsythoside A can ease psoriasis-like dermatitis by suppressing the secretion or expression of IL-6 and IL-17." (PMID 35055377, 2022).